TWF2 (twinfilin actin binding protein 2)
Description:
Actin-binding protein involved in motile and morphological processes. Inhibits actin polymerization, likely by sequestering G-actin. By capping the barbed ends of filaments, it also regulates motility. Seems to play an important role in clathrin-mediated endocytosis and distribution of endocytic organelles. May play a role in regulating the mature length of the middle and short rows of stereocilia (By similarity).
Synonyms: PTK9L; MSTP011; A6RP; A6r
Tractability: PROTAC: ubiquitination databases record sites on it; its protein half-life has been measured.
Gene: Protein-coding gene on chromosome 3 (52,228,612 to 52,246,788, reverse strand). Ensembl gene ENSG00000247596.
Subcellular location: Cytoplasm, cytoskeleton; Cytoplasm, perinuclear region; Cell projection, stereocilium
Subcellular location (Human Protein Atlas): Plasma membrane
Pathways (Reactome):
Sensory Perception: Sensory processing of sound by inner hair cells of the cochlea; Sensory processing of sound by outer hair cells of the cochlea
Gene Ontology:
Molecular function: ATP binding; cadherin binding; protein binding; protein kinase C binding; RNA binding; actin filament binding; actin monomer binding; phosphatidylinositol-4,5-bisphosphate binding; actin binding
Biological process: cellular response to growth factor stimulus; cellular response to retinoic acid; positive regulation of axon extension; positive regulation of lamellipodium assembly; positive regulation of neuron projection development; regulation of actin cytoskeleton organization; actin filament depolymerization; barbed-end actin filament capping; negative regulation of actin filament polymerization; regulation of lamellipodium assembly; regulation of microvillus length
Cellular component: cytoplasm; extracellular exosome; growth cone; actin filament; filopodium; lamellipodium; myofibril; perinuclear region of cytoplasm; stereocilium; cytoskeleton
Genetic constraint (gnomAD): Loss-of-function variants: 15 observed, 44.02 expected, observed/expected ratio (o/e) 0.34, 90% interval 0.23 to 0.52. The upper end of that interval is the gene's LOEUF score, 0.52, which puts it in group 2 of 6, group 1 being the genes least tolerant of losing a copy. Missense variants: 423 observed, 473.81 expected, observed/expected ratio (o/e) 0.89, 90% interval 0.82 to 0.97. Synonymous variants: 177 observed, 198.66 expected, observed/expected ratio (o/e) 0.89, 90% interval 0.79 to 1.01.
Homologues: Orthologues: chimpanzee TWF2 (99% identical), macaque TWF2 (99% identical), pig TWF2 (97% identical), mouse Twf2 (97% identical), dog TWF2 (96% identical), guinea pig TWF2 (96% identical), rabbit TWF2 (95% identical), tropical clawed frog twf2 (78% identical), zebrafish twf2a (72% identical), zebrafish twf2b (70% identical), rat Twf2 (65% identical), Drosophila melanogaster twf (49% identical), and 1 more. Paralogues in human: TWF1 (65% identical).
Diseases named in the same sentence as TWF2 in open-access papers:
TWF2 is named in the same sentence as 13 diseases in open-access papers, as found by Europe PMC text mining. Sharing a sentence is not in itself a finding about the gene and the disease. The quoted sentences say what the papers report.
hepatocellular carcinoma (3 papers, 2022 to 2025). A malignant tumor that arises from hepatocytes. "TWF2 deficiency correlates with decreased invasive and migratory capacity of the human hepatocellular carcinoma cell line HUH-7." (PMID 36497164, 2022). "When CHAF1B was knocked down, the protein and mRNA levels of TWF2 were considerably reduced in the human hepatocellular carcinoma cell line HUH-7, thus decreasing the invasion and migration of the tumor." (PMID 36128444, 2022).
breast carcinoma (2 papers, 2022 to 2025). "When TWF2 expression in clear cell RCC was compared to that in healthy tissues, we determined that it was much higher than that in healthy tissues, whereas it was much lower in colon cancer, LUAD, and breast cancer tissues (p < 0.01)." (PMID 36128444, 2022).
ovarian carcinoma (1 paper, 2022). A malignant neoplasm originating from the surface ovarian epithelium. "In contrast, we discovered a statistically significant difference between high TWF2 transcription levels and improved OS for lung and ovarian cancers." (PMID 36128444, 2022).
renal cell carcinoma (1 paper, 2025). "Twinfilin actin‐binding protein (TWF2) is upregulated in sunitinib‐resistant renal cell carcinoma (RCC) cells, where it interacts with YAP and protects YAP from degradation." (PMID 40948085, 2025).
cancer (4 papers, 2015 to 2022). A tumor composed of atypical neoplastic, often pleomorphic cells that invade other tissues. "According to survival analysis, TWF2 transcription was found to be associated with poor prognosis in various forms of cancer." (PMID 36128444, 2022). "Genomic changes in TWF2 have been observed in tumor samples spanning a variety of cancer types, including deletions, amplifications, and mutations." (PMID 36128444, 2022). "TWF2 was positively associated with cancer-associated fibroblasts in STAD and TGCT and with endothelial cells in LUAD, LUSC, and STAD." (PMID 36128444, 2022). "TWF2 transcription was associated with poorer OS in several forms of cancer, including LAML (p = 0.03), LGG (p < 0.0001), and LIHC (p = 0.01)." (PMID 36128444, 2022). "TWF2 transcription in cancers and the number of TWF2 mutations were examined as part of our study." (PMID 36128444, 2022). "We utilized the The Cancer Genome Atlas and Gene Expression Omnibus datasets to investigate the role of TWF2 in different types of cancers." (PMID 36128444, 2022). "When comparing TWF2 transcription profiles across different types of cancers, the survival status, genetic alterations, and essential biological pathways were all considered." (PMID 36128444, 2022). "TWF2 transcription, MSI, and tumor mutational burden have been found to be positively associated with various cancers." (PMID 36128444, 2022). "Our pan-cancer analysis provided a complete overview of the oncogenic effects of TWF2 in a wide range of human malignancies." (PMID 36128444, 2022). "The transcription profile of TWF2 was investigated in a pan-cancer analysis using data from TCGA and GEO databases." (PMID 36128444, 2022). "TWF2 mainly participates in cancer cell proliferation signalling pathways through interaction with chromogranin B (CHGB)." (PMID 26515236, 2015). "In addition, we noted that “deep deletion” of TWF2 in tumors frequently occurs in almost all cancer types." (PMID 36128444, 2022). "So far, there have been few studies related to TWF2 in the field of cancer research." (PMID 36128444, 2022). "TWF2’s role in cancer development, on the other hand, remained a mystery." (PMID 36128444, 2022). "Thus, TWF2 may be one of an indicator for cancer patients’ prognosis, which is supported by these findings." (PMID 36128444, 2022). "Therefore, we conducted a TWF2 pan-cancer analysis in this study." (PMID 36128444, 2022). "TWF2 overexpression was also reported to be related to poorer prognosis in patients with cancers such as LAML, LGG, LIHC, HNSC, and KIRC, which express a high level of TWF2." (PMID 36128444, 2022). "TWF2’s role in cancer remains largely unknown, no comprehensive pan-cancer studies have been conducted." (PMID 36128444, 2022).
tumor (4 papers, 2016 to 2025). "Sunitinib administration led to significantly reduced tumor growth and volume in the TWF2‐deficient group, as monitored weekly via in vivo imaging." (PMID 40948085, 2025). "Our data showed that TWF2 transcription is positively correlated with the number of endothelial and tumor-associated fibroblast cells that have been deconvolved using several immunodeconvolution methods." (PMID 36128444, 2022). "TWF2 transcription was found to be statistically associated with clinical prognosis, immune cell infiltration, MSI, and tumor mutation burden in a range of human malignancies, helping to clarify the role of TWF2 in carcinogenesis from various perspectives." (PMID 36128444, 2022). "Mutation of the M99 residue abolishes the tumor‐promoting activity of TWF2." (PMID 40948085, 2025). "Immunohistochemical analysis of paired ccRCC samples from the SYSU cohort further supported the significant upregulation of TWF2 in tumor tissues, especially among patients with sunitinib resistance." (PMID 40948085, 2025). "Collectively, these results establish Met99 as a critical mediator of TWF2‐driven tumor progression and therapeutic resistance in RCC." (PMID 40948085, 2025). "Analysis of TCGA–KIRC dataset revealed significantly upregulated TWF2 expression in tumor tissues relative to normal controls." (PMID 40948085, 2025). "In vivo validation using a xenograft mouse model demonstrated that overexpression of wild‐type TWF2 resulted in increased tumor burden following sunitinib treatment, whereas the M99A mutant failed to induce resistance." (PMID 40948085, 2025). "The functional importance of YAP in mediating TWF2‐driven tumor progression and drug resistance was further validated." (PMID 40948085, 2025). "This study aims to identify Twinfilin actin‐binding protein (TWF2) as a key mediator of tumor aggressiveness and therapeutic resistance." (PMID 40948085, 2025). "In vivo, an orthotopic RCC tumor model was established using luciferase‐labeled TWF2‐knockdown and control 786‐O‐R cells in BALB/c nude mice." (PMID 40948085, 2025). "A correlation between higher TWF2 transcription and advanced tumor pathological staging was found using the GEPIA2 program in KICH and PAAD (all p < 0.05)." (PMID 36128444, 2022). "The transcription patterns of TWF2 in various cell lines and non-tumor tissues were investigated in greater depth." (PMID 36128444, 2022). "Then, using data from TCGA and GEO datasets, we investigated the relationship between TWF2 transcription and the prognosis of various tumor patients." (PMID 36128444, 2022). "Using TCGA tumor samples, we examined the correlation between the transcription of TWF2, MSI, and TMB." (PMID 36128444, 2022). "The large-scale proteome program from the CPTAC (National Cancer Institute’s Clinical Proteomic Tumor Analysis Consortium) enabled us to analyze TWF2 at the protein level, in addition to its transcription." (PMID 36128444, 2022). "Validation using the SYSU ccRCC cohort confirmed elevated TWF2 expression at both mRNA and protein levels in tumor tissues compared to adjacent normal tissues, as demonstrated using real‐time quantitative polymerase chain reaction (RT‐qPCR) and western blotting." (PMID 40948085, 2025). "Depending on the type of tumor, the TWF2 transcription level can vary significantly." (PMID 36128444, 2022). "It is unclear whether TWF2 is involved in the oncogenesis of specific tumor types or whether it is involved in more general pathways that contribute to tumor pathogenesis." (PMID 36128444, 2022). "First, with further studying, the relationship between TWF2 and tumor may become clearer and closer." (PMID 36128444, 2022). "Therefore, we decided to investigate TWF2 genetic changes in human tumor tissues." (PMID 36128444, 2022). "TWF2 transcription variations between tumor and non-tumor tissues were further examined using the GTEx dataset in cases where TCGA data were unavailable." (PMID 36128444, 2022).
TWF2 also shares sentences with these, for which no sentence is quoted: breast tumors (1 paper); colon cancer (1); colorectal cancer (1); diabetes (1); lung carcinoma (1); respiratory disease (1); skin cancer (1).